EGFR (epidermal growth factor receptor)
Diseases named in the same sentence as EGFR in open-access papers (continued):
Sharing a sentence is not in itself a finding about the gene and the disease.
liver fibrosis (continued). "In this study, the effects of PL on the regulation of EGFR and STAT3 were investigated in carbon tetrachloride (CCl4) induced liver fibrosis and hepatic stellate cells (HSC-T6)." (PMID 26550019, 2015). "Of which, core targets (EGFR, STAT3, JAK1) all are enriched in cancer signaling pathways, given their high connectivity in the PPI network and established crosstalk in liver fibrosis, we hypothesized that PZH modulates the EGFR/JAK1/STAT3 signaling axis." (PMID 41181146, 2025). "Previous studies have revealed that EGFR signaling activation induces hepatocyte epithelial-mesenchymal transition and PDGFR activation is essential for hepatic stellate cell activation, contributing to the development of liver fibrosis." (PMID 40789837, 2025). "Considering core targets of the PPI network and a network of the common targets and pathways enriched, AKT1, MAPK1, EGFR, MTOR, and SRC may be the core potential targets of CL against hepatic fibrosis." (PMID 37478207, 2023). "Both curcumin and demethoxycurcumin were strongly bound to MAPK1, EGFR, and SRC, which indicated that curcumin and demethoxycurcumin might be the core components against hepatic fibrosis, and MAPK1, EGFR, and SRC might be the core targets." (PMID 37478207, 2023). "The results revealed that quercetin and luteolin could activate the PI3K-Akt signaling pathway and inhibit liver fibrosis by binding to hub targets, including AKT1, CCND1, EGFR, MAPK1, MYC, and RELA." (PMID 37083803, 2023). "Considering the main targets showed by PPI network, we speculate that AKT1, MAPK1, EGFR, MTOR, and SRC may be the core potential targets of CL against hepatic fibrosis, and molecular docking was further performed." (PMID 37478207, 2023). "Molecularly, Smad4 expression in hepatocytes upregulated the expression of ID1 and further enhanced the paracrine activity of CTGF; subsequently, mediated by EGFR, CTGF promoted HSCs’ activation by regulating the p38 and p65 signaling pathways, which in turn led to liver fibrosis." (PMID 36232998, 2022). "EGFR and TGF-beta signalling pathways were enriched in liver fibrosis." (PMID 32494274, 2020). "Pdgf-c Tg mice treated at 9 weeks of age (liver fibrosis) and 32 weeks (HCC) with locked nucleic acid anti-miR-214 showed a marked reduction in fibrosis and tumor incidence and these effects were attributed to repression of EGFR and TGF-β signaling pathways." (PMID 31739536, 2019). "Moreover, there were 192 potential targets regulated by DSLHG, of which 86 were related to liver fibrosis, including AKT1, EGFR, and IGF1R." (PMID 31354851, 2019). "Importantly, deletion of EGFR phenocopied deletion of STAT3 and led to aggravated liver damage, liver fibrosis, and hyperproliferation of K19+ cholangiocytes." (PMID 27568040, 2017). "In the classic CCl4-induced liver fibrosis mouse model, BMP7 antifibrotic effects have been proposed to rely on its crosstalk with EGFR and TGF-β1, by suppressing their expression and inhibiting activation of EGFR and abolishing the accumulation of hepatocyte-derived fibroblasts via EMT." (PMID 29295498, 2017). "AlfpCre Mdr2−/− mice were comparable to Mdr2−/− mice demonstrating that aggravated liver fibrosis is due to EGFR deletion but not AlfpCre transgene expression." (PMID 27568040, 2017). "Although the present study focused on the effect of MD-1 by inhibiting EGFR activation, other signaling pathways, such as the Ras/ERK pathway, may also be involved in hepatic fibrosis." (PMID 27342773, 2016). "Furthermore, the epidermal growth factor receptor (EGFR) and its interactive signaling partner Erb-B2 receptor tyrosine kinase 3 (ERBB3) axis in hepatocytes is essential for the recruitment of profibrotic Ly6Chi monocytes in CCl4-induced liver fibrosis." (PMID 41479922, 2025). "Therefore, Hugan tablets may inhibit the activation of the PI3K-Akt signaling pathway through IL-6, AKT1, VEGFA, EGFR, and MAPK3, thereby inhibiting the activation of HSCs and delaying the occurrence of liver fibrosis." (PMID 34262454, 2021).
liver fibrosis (continued). "Although these results suggest that EGFR inhibition might be a new therapeutic approach during liver fibrosis, the roles of EGFR and its ligands in CLAD after transplantation are not completely understood thus far." (PMID 28053995, 2016). "However, the application of PL for the treatment of liver fibrosis has not been evaluated in liver fibrosis model, especially the regulation of EGFR/STAT3 pathway in fibrotic liver." (PMID 26550019, 2015). "Moreover, miR-214 also enhances the activity of the EGFR and TGF-β signaling pathways by targeting Mig6, a negative regulator of EGFR signaling, thereby promoting HSC activation and liver fibrosis." (PMID 33994867, 2021). "However, its role in regulation of EGFR and STAT3 during liver fibrosis has not been investigated." (PMID 26550019, 2015).
metastatic carcinoma (61 papers, 2006 to 2025). A carcinoma which has spread from the original site of growth to another anatomic site. "The first example is the treatment of metastatic cancer caused by the overexpression of EGFR using two anti EGFR antibodies, Cetuximab (IgG1) and Panitumumab (IgG2)." (PMID 35842448, 2022). "The Epidermal Growth Factor Receptor (EGFR) is frequently mutated and overexpressed in metastatic cancer." (PMID 29464085, 2018). "Another FDA approved (2007) HER-targeting drug for metastatic cancer is lapatinib, a kinase inhibitor of both the epidermal growth factor receptor (EGFR) and HER2." (PMID 38088952, 2024). "EGFR has numerous kinase-independent roles, one of which is accomplished through the Sorting Nexin-dependent retrotranslocation of EGFR to the nucleus, which is observed in some metastatic cancers and therapeutically resistant disease." (PMID 36253541, 2023). "•EGFR, POLE, and PB1 genes had high mutated frequency in the patients with relapse and metastatic cancer." (PMID 37515929, 2023). "Anti‐epidermal growth factor receptor (anti‐EGFR) monoclonal antibodies, such as cetuximab and panitumumab, are used to treat metastatic cancer that expresses EGFR." (PMID 37452615, 2023). "For these metastatic cancer patients, targeted therapy such as EGFR and ALK inhibitors have been developed, but they only show favorable efficiency to specific patients with EGFR and ALK mutations." (PMID 37583701, 2023). "About 90% of patients with metastatic cancer had treatment failure due to acquired resistance to chemotherapy, including resistance to epidermal growth factor receptor (EGFR) antagonists." (PMID 35408492, 2022). "Oleic acid prompts cell proliferation and migration in metastatic cancer through various pathways, including EGFR, AKT and NF-κB." (PMID 32344578, 2020). "Clinicians use anti-epidermal growth factor receptor (EGFR) therapy and immune checkpoint inhibitors along with traditional cytotoxic chemotherapy in patients with recurrent or metastatic cancer." (PMID 32718084, 2020). "LY3164530 is a bispecific antibody that targets mesenchymal-epithelial transition factor (MET) and EGFR for treating advanced and metastatic cancer that recently underwent phase I trials." (PMID 32630411, 2020). "We used an affibody molecule, which is an antibody mimetic, instead of using an antibody to target HER2 or EGFR in metastatic cancer cells." (PMID 30669481, 2019). "We demonstrated that combining 99mTc-phytate scintigraphy and anti-EGFR affibody NIR fluorescence imaging can efficiently identify metastatic cancer cells in lymph nodes in real time." (PMID 30669481, 2019). "It seems likely that the anti-EGFR affibody probe accumulated in the metastatic cancer cells in the lymph nodes for a certain long duration while the probes were gradually washed away from the nonmetastatic lymph nodes." (PMID 30669481, 2019). "Epidermal growth factor receptor (EGFR) is one of the major targets of cancer treatment, because increases in the expression and activation levels of EGFR are frequently found in several metastatic cancers." (PMID 29462206, 2018). "EGFR/AKT-mediated signaling is involved in different metastatic cancers, and its role in chemoresistance is well documented." (PMID 30148841, 2018). "EGFR/AKT-mediated signaling is involved in different metastatic cancers and its purported role in chemoresistance is well-documented." (PMID 29234489, 2017). "The EGFR transcript was identified in 3 patients (42.8%) undergoing systemic therapy for metastatic cancer." (PMID 27479125, 2016). "Only one patient with metastatic cancer received target therapy of anti-EGFR monoclonal antibody cetuximab." (PMID 27121310, 2016).
metastatic carcinoma (continued). "Comparison of CTCs isolated by CellSearch or magnetic beads coated with anti-EpCAM, anti-EGFR or anti-FGFR from patients with metastatic cancer." (PMID 27711186, 2016). "Recently, some studies have reported that EGFR inhibitors are effective first-line therapeutic agents in the treatment of some metastatic cancers." (PMID 19835603, 2009). "EGFR is the first antitumor target to be identified, and known to be overexpressed in most of the TNBC and inflammatory breast cancers, but associated with paradoxical function in metastatic cancer progression." (PMID 41048341, 2025). "In this study, we highlight lipids as pivotal post-translational modification substrates that promote EGFR protein stability and PM localization in a palmitoylation-dependent manner and enhance metastatic cancer cell stemness beyond their original functions as energy sources and signaling mediators." (PMID 38263401, 2024). "Additionally, it also possesses the capability of disrupting the function of actin cytoskeleton and the EGFR signaling system which then affects the progressive ability of metastatic cancer development." (PMID 32823904, 2020). "Moreover, we were able to efficiently isolate CTCs from patients with metastatic cancer with magnetic beads functionalised with anti-EGFR antibodies." (PMID 27711186, 2016). "MenaINV-induced increases in haptotaxis and matrix degradation in response to insoluble ligands provide additional mechanisms by which metastatic cancer cells may resist EGFR inhibitor treatment." (PMID 27824079, 2016). "Erlotinib (Tarceva) is a human epidermal growth factor receptortype 1/epidermal growth factor receptor (HER1/EGFR) tyrosine kinase inhibitor initially approved by the US Foodand Drug Administration in the treatment of patients with locally advanced or metastatic cancer." (PMID 20302205, 2010). "Anti-PD-1/PD-L1 inhibitors were identified as a preferable treatment option for advanced or metastatic cancer patients who are male, aged < 65 years, current or former smokers, had no CNS or liver metastasis, had not EGFR mutation, and had high PD-L1 expression." (PMID 32034198, 2020). "However, in metastatic cancers, biological heterogeneity among tumour cells pre-exists at the time of clinical presentation and tumors resistant to EGFR-TKIs may be composed of a heterogeneous mix of TKI-sensitive and TKI-resistant cells." (PMID 27336903, 2016). "As a radiation sensitizer for patients with recurrent or metastatic cancer, the FDA has approved cetuximab, a monoclonal antibody that targets the epidermal growth factor receptor (EGFR; also known as HER1)." (PMID 39308526, 2024). "For example, cetuximab and bevacizumab, existing effects in impairing tumor vasculature by blocking EGFR and VEGF, respectively, have been approved by the US Food and Drug Administration (FDA) and commercially applied in treatment of metastatic cancers." (PMID 32824997, 2020). "The primary tumors of many metastatic cancers display increased expression of key proteins involved in invadopodia formation (e.g. Tks5, EGFR), compared to non-metastatic cancers." (PMID 34094984, 2021). "A group of monoclonal antibodies with or without chemotherapy have been developed to target EGFR in patients with metastatic cancers." (PMID 33247675, 2020). "Two highly studied RTK signaling pathways, the epidermal growth factor receptor (EGFR; Entrez Gene: 1956) pathway and the hepatocyte growth factor receptor (HGFR or c-Met; Entrez Gene: 4233) pathway, have been identified as therapeutic targets for preventing and treating metastatic cancer." (PMID 27127175, 2016). "Epidermal growth factor receptor (EGFR) amplification and alterations in the transforming growth factor-β (TGF-β) signal transduction network, for example, frequently accompany epithelial tumor progression from a benign or noninvasive lesion to an aggressive, metastatic carcinoma." (PMID 22454771, 2012).
renal fibrosis (60 papers, 2012 to 2025). A final common manifestation of a wide variety of chronic kidney diseases characterized by glomerulosclerosis and tubulointerstitial fibrosis. "While EGFR stimulation is associated with renal fibrosis in other clinical conditions, its role during acute and long-term SARS-CoV-2 infection is not fully understood." (PMID 38932130, 2024). "Here, we demonstrated that elevated EGFR signaling causes renal fibrosis and apoptosis in diabetic rats." (PMID 39194535, 2024). "Abnormal phosphorylation patterns in signaling proteins, notably those implicated in the epidermal growth factor receptor (EGFR) pathway, are linked to renal fibrosis, which marks the course of CKD." (PMID 39728069, 2024). "For example, Aldo-induced ROS generation and renal fibrosis are linked to epidermal growth factor receptor (EGFR) activation." (PMID 34200377, 2021). "In conclusion, in vivo, our findings show a critical role for the inhibitory effect of PrdxV in EGFR/Stat3 activation associated with the development of renal fibrosis after UUO." (PMID 31217524, 2019). "Moreover, EGFR-targeted therapies in animal models have shown potential in managing PKD and renal fibrosis, while EGFR antagonists have been associated with drug-induced nephrotoxicity." (PMID 41155421, 2025). "Further investigation revealed that renal fibrosis caused by unilateral ureteral obstruction, renal hypertension, subtotal nephrectomy, or angiotensin II/endothelin-triggered kidney damage requires sustained EGFR activation as an essential step." (PMID 39194535, 2024). "The detrimental role of EGFR in GN is supported by a study in a type 2 diabetes mouse model where EGFR inhibition with Erlotinib (a selective, clinically used EGFR inhibitor) resulted in decreased albuminuria and glomerulosclerosis, attenuated podocyte loss, and reduced renal fibrosis." (PMID 39234105, 2024). "Meanwhile, although HUWE1 has been reported to mediate EGFR ubiquitination and degradation in renal fibrosis inhibition, their association in cancer remains unclear." (PMID 37813845, 2023). "Although EGFR activation is crucial for kidney physiology and repair such as following acute kidney injury through mechanisms involving dedifferentiation, migration and proliferation of tubular cells, its sustained activation has been linked to renal fibrosis via activation of myofibroblasts." (PMID 39234105, 2024). "Moreover, our previous studies demonstrated that pharmaceutical and genetic blockade of EGFR leads to dephosphorylation of STAT3 and ERK1/2 and attenuation of renal fibrosis; pharmaceutical inhibition of EGFR/ERK signaling is associated with reduction of peritoneal fibrosis." (PMID 31727005, 2019). "Previous studies have implicated CL-11, EGFR, and TGF-β signaling in fibroblast proliferation and renal fibrosis in murine models." (PMID 40895578, 2025). "In the USP11 knockout mouse model of renal fibrosis, the degradation of EGFR was increased, which inhibited downstream signaling pathways and delayed the renal fibrosis and epithelial-mesenchymal transition." (PMID 40225869, 2025). "We employed our surrogate mouse model to determine the extent to which EGFR stimulation is responsible for renal fibrosis in COVID-19 disease." (PMID 38932130, 2024). "E3 ligase plays a regulatory role in a variety of diseases and tumors by regulating EGFR signaling pathway, UPS11 promotes renal fibrosis by deubiquitination of EGFR." (PMID 39075515, 2024). "An EGFR mimotope (that prevents downstream signaling) alleviated renal fibrosis in the murine unilateral ureteral obstruction model." (PMID 39234105, 2024). "SRT1720, a potent activator of SIRT1, promotes renal fibrosis via increased phosphorylation of epidermal growth factor receptor (EGFR) and platelet-derived growth factor receptor β (PDGFRβ)." (PMID 39335456, 2024).